PCNA (proliferating cell nuclear antigen)
Diseases named in the same sentence as PCNA in open-access papers (continued):
Sharing a sentence is not in itself a finding about the gene and the disease.
tumor (continued). "Western blotting showed JP3 treatment down-regulated expressions of MMP2, CD31 and PCNA significantly in GC tumor tissues; IHC data showed that JP3 suppressed expressions of CD31 (microvessel density (MVD)) and Ki-67 in GC tumor tissues." (PMID 32576271, 2020). "Compared with the control group, the subcutaneous xenograft mouse model results showed that animals injected with MYH9-silenced cells displayed reduced tumor burden and reduced Ki67 and PCNA expression levels." (PMID 32296025, 2020). "IHC analyses of tumor tissues showed that eEF2K depletion increased the expression of proliferating cell nuclear antigen (PCNA), a marker of cell proliferation." (PMID 32054489, 2020). "In agreement, the proliferative capacity of the HCC cells was seriously compromised after regorafenib/A-1331852 co-administration for four weeks, as denoted by PCNA staining of tumor biopsies." (PMID 32024199, 2020). "Next, western blot analysis showed that expression of KI67 and PCNA in tumor tissues was downregulated in response to injection with Exo-miR-144 agomir, compared to findings with Eco-NC agomir (p < 0.05)." (PMID 32102682, 2020). "By investigating two independent tumor cohorts of HGSC and OPSCC, respectively, we found that strong IGF1R/PCNA colocalization was significantly associated with better overall survival." (PMID 32701997, 2020). "TUNEL assay and immunohistochemistry assay showed that intravenous‐injected hAMSCs significantly increased TUNEL‐positive cells and decreased PCNA‐positive cells in tumour tissues compared with the PBS groups." (PMID 32798252, 2020). "Moreover, the continuous activation of STAT3 in tumor cells can enhance the expression of genes associated with cell survival, proliferation, and growth, including B-cell lymphoma-2 (Bcl-2), proliferating cell nuclear antigen (PCNA), and vascular endothelial growth factor (VEGF)." (PMID 32784751, 2020). "We also examined the proliferation marker PCNA and the pro-apoptotic protein Bcl-2 to assess the effects of C10 treatment on the proliferation and apoptosis of the tumor xenografts." (PMID 32427575, 2020). "Previous studies have revealed that the PCNA positive cells decreased in number in tumor cells when treated with the quinone-based compounds." (PMID 31357586, 2019). "Recently, the NKp44 binding site for PCNA was identified and an NKp44-derived peptide has been shown to target intracellular PCNA, resulting in the apoptosis of cancer cell lines in vitro and tumor growth arrest in vivo." (PMID 31024551, 2019). "The apoptotic effect was also identified via the increased expression of the cleaved caspase-3 and decreased expression of the cell proliferation marker PCNA in HCC tumor spheroids." (PMID 31885640, 2019). "Then we also found that the significant decrease expression of PCNA protein in the SMYD2 knockdown tumor tissues of mice." (PMID 31548876, 2019). "As2O3-NPs inhibited tumor growth more strongly than As2O3 or control, a finding likely attributed to the downregulation of PCNA and DNMT-related proteins and the upregulation of GSDME-N." (PMID 31637008, 2019). "The percentage of tumor cells expressing PCNA protein in the IT group was significantly lower than in the INT group (p<0.01)." (PMID 32695310, 2019). "When intraperitoneally administrated on colon tumor cell in vivo, they showed decreases in the tumor volumes, tumor sizes and the cell nuclear antigen (PCNA) protein levels." (PMID 30609771, 2019). "In excised tumors, we observed a significant decrease of tumor cell proliferation as shown by the results of Ki-67 and PCNA staining." (PMID 31803360, 2019). "Western blot analysis validated that the expression levels of PCNA were decreased in the group of mice tumor samples treated with siPCNAP1 and siPCNA." (PMID 31410212, 2019). "RSV significantly suppressed tumor growth in vivo and decreased the proportion of cells showing expression of proliferating cell nuclear antigen (PCNA) and α-smooth muscle actin (α-SMA)." (PMID 31013842, 2019).
tumor (continued). "We then further analyzed the growth inhibitory effects of these two polyphenols in tumor tissue by performing immunohistochemistry for PCNA." (PMID 31143704, 2019). "Our IHC analysis demonstrated considerable inhibition of PCNA expression in VERU-111 treated tumor tissues compared to vehicle control treated tumors." (PMID 30674344, 2019). "The nude mouse xenograft model confirmed QKI‐6’s anti‐tumour activity in vivo, as evidenced by reduced tumour xenograft growth and increased expression of Ki67 and PCNA." (PMID 31449345, 2019). "Immunofluorescent staining and immunoblot of PCNA showed that KYA1797K effectively suppressed proliferation in tumor tissue in contrast to erlotinib." (PMID 30679620, 2019). "IHC showed that CDCA5 knockdown (P < 0.05 vs. sh-Ctrl) significantly decreased proliferating cell nuclear antigen (PCNA) expression in xenograft tumor (P < 0.05 vs. sh-Ctrl)." (PMID 30808873, 2019). "It suggests that PCNAP1 up-regulates the expression of PCNA by competing for the tumor-suppressive miR-154." (PMID 31410212, 2019). "In tumor tissue, we performed immunohistochemistry and confirmed the findings by western blot, to determine the effects of progesterone on markers of tumor proliferation (PCNA), angiogenesis (VWF), and apoptosis (cleaved caspase-3)." (PMID 30700763, 2019). "In order to correlate patient’s disease staging with our NTN4 immunohistochemistry analysis, we organized the results in relation to PCNA expression levels, age, tumor stage, patient status, gender and primary tumor sites." (PMID 30160193, 2019). "Positive expressions of AFP, Ki-67 and PCNA were detected by immunohistochemistry in tumor tissues, which were markedly upregulated by circRNA Cdr1as overexpression." (PMID 31581132, 2019). "H4R agonists (histamine, Clozapine, JNJ28610244): ↓ tumor growth, ↓ mitotic index, and PCNA in tumor, ↓ metastatic spread, and angiogenesis." (PMID 31231212, 2019). "The MORC2-C/EBPα-WT group get markedly heavier in tumor weight and larger volume, and showed stronger PCNA staining (down panel) than MORC2-C/EBPα-K161R group." (PMID 30644437, 2019). "The intensity of PCNA staining was significantly increased in both the normal and tumor sections of AAV-CD36-KD group than were in the control group." (PMID 31484922, 2019). "Based on staining for PCNA+ hepatocytes, we found a significant promotion of tumor cell proliferation by myostatin inhibition." (PMID 30718259, 2019). "Consistently, tumors formed in AAV-CD36-KD group showed significantly more proliferating cells as evidenced by higher proportions of Ki-67 and PCNA staining in both normal mucosa and tumor sections." (PMID 31484922, 2019). "By contrast, PCNA and Ki67 staining showed that the number of Ki67 positive tumor cells was substantially less in tumors of NV669-treated mice, when compared with control tumors." (PMID 31803360, 2019). "Tumor cells at the periphery of the lesions were highly infiltrative, and many mitotic figures and high PCNA positivity (68.2%) were observed, suggesting a high proliferation index." (PMID 31015491, 2019). "P21(Cip1/Waf1) is a well-known tumor-suppressor that arrests cell cycle progression by disrupting CDK/cyclins complexes and by associating to proliferating cell nuclear antigen (PCNA)." (PMID 31799185, 2019). "Like Cyclin-D1, tumor cells in both the control as well as the Rapamycin-treated groups were positive for PCNA." (PMID 30863496, 2019). "For instance, overexpression of proliferating cell nuclear antigen (PCNA) by tumor cells impaired NKp44-mediated NK cell attack in an in vitro model." (PMID 31053876, 2019). "The tumor section in the Ehrlich group shows a moderate positive reaction for PCNA expression, while mild to moderate positive reactions for PCNA expression were detected in Ehrlich cotreated with Avns." (PMID 30755785, 2019). "To study further the effect of ovarian steroids on tumor cell proliferation, we analyzed the expression of PCNA by immunohistochemistry (IHC)." (PMID 30738018, 2019).
tumor (continued). "For the immunohistochemical experiment, tumor tissue was incubated with primary antibodies against proliferating cell nuclear antigen (PCNA) overnight at 4°C." (PMID 31001469, 2019). "Interestingly, the decrease in tumor size in pterostilbene was associated with tumor cell apoptosis, as indicated by an upregulation of activated caspase-3 whereas in resveratrol-treated mice it was accompanied by arrest of cell cycle, as indicated by a downregulation of PCNA." (PMID 31143704, 2019). "Accordingly, the levels of PCNA and Bcl‐2 were significantly lower in xenograft tumour tissues collected from the SNHG16 knockdown than the control group (P < .05)." (PMID 31483572, 2019). "As expected, the combined treatment also upregulated the expression of pro-apoptotic protein Bak and decreased the expression of cell proliferation marker PCNA in tumor tissues, indicating an additive effect of the two inhibitors." (PMID 31601253, 2019). "We assessed the combinatorial effects of PCNA-I1S with DNA damage agents on tumor cell growth using the MTT assay." (PMID 31600334, 2019). "Immunohistochemical analysis revealed that PCNA, a proliferation marker, was significantly decreased in miR-126 overexpressing tumor cells." (PMID 31245291, 2019). "Nano-DOX also suppressed the expression of Ki67 and PCNA, markers of tumor cell proliferation and growth, to a lesser degree than DOX." (PMID 31623629, 2019). "Targeting PCNA in replisomes with monoclonal antibodies triggers lethal DNA replication stress in tumor cells." (PMID 31600334, 2019). "In all cases, epithelial islands at the tumour front had a periphery of intensely stained PCNA positive epithelial cells, surrounding prickle cells." (PMID 31672124, 2019). "The PCNA-positive tumor cells in the group of αM/MPEG-PCL nanomicelles were markedly lower than the ones in other groups." (PMID 30770785, 2019). "In all cases, tumour islands had a periphery of intensely stained proliferating cell nuclear antigen-positive epithelial cells." (PMID 31672124, 2019). "The measurement of in vitro tumor cell inhibition by PCNA-Is in MTT assay correlates closely with the measurement of cytotoxic activity of the compounds in colony formation assay and apoptosis assay." (PMID 31600334, 2019). "In vivo studies showed that knockdown of hsa_circ_006100 delayed tumour growth, reduced PCNA expression and upregulated miR‐195 and BCL‐2 expression which was restored by miR‐195 inhibition due to GPRC5A/EGFR signalling, and changed the EMT phenotype in vivo." (PMID 31318114, 2019). "Fra-1 and c-Fos overexpression together with PCNA immunoreaction are clearly observed in tumor samples, whereas PCNA immunoreactivity and c-Fos and Fra-1 expression levels are almost undetectable in the non-pathological counterparts." (PMID 31275861, 2019). "PCNA (nuclear) staining was obvious indicating the proliferative nature of the tumor with radiotracer uptake." (PMID 31119488, 2019). "Decreased expression levels of the proliferation-related genes PCNA and cyclin D1 were observed in the tumor tissues of Ct55 knockout mice by qRT-PCR." (PMID 30944312, 2019). "The staining of formalin‐fixed paraffin‐embedded (FFPE) subcutaneous tumour tissues with proliferating cell nuclear antigen (PCNA) confirmed the lower proliferation status of LUCAT1 knockdown cells." (PMID 30588744, 2019). "IL-33 has also been shown to promote tumor cell growth, colony formation and expression of Ki-67 and proliferating cell nuclear antigen (PCNA) in a PGE2 dependant manner." (PMID 31231372, 2019). "Consistently, we also found that the percentages of β-catenin-, PCNA- and cyclin D1-positive cells in the tumor tissues of Ct55 knockout mice were lower than those in the WT mice after AOM/DSS treatment." (PMID 30944312, 2019). "To evaluate more definitively the function of fibroblasts activated by Nodal, we collected the tumor tissues and detected the quantity of CAFs and the expression of PCNA by IHC." (PMID 31167491, 2019).
tumor (continued). "We further examined the expression of cell proliferation marker, Ki-67 and PCNA in the neoplasms of both CT and VT mice as well as normal colorectal epithelia with IHC analysis." (PMID 30665389, 2019). "It suggests that miR-154 as a potential tumor suppressor is involved in modulation of PCNAP1/PCNA signaling." (PMID 31410212, 2019). "In the study, YFTL induced apoptosis as indicated by TUNEL staining in tumor tissues and reduced the expression of two proliferation markers, PCNA and Ki-67." (PMID 30781674, 2019). "In particular, NK cell-treated tumors showed larger necrotic areas and lower quantities of PCNA-positive proliferating tumor cells than tumors treated with gemcitabine." (PMID 31324057, 2019). "The significant decrease in the expression of PCNA in the tumor samples shows a condensation and fragmentation of the nuclei, thus an antiproliferative action." (PMID 31850224, 2019). "IHC staining showed that PCNA was upregulated in lncRNA-HGBC-overexpressing xenograft tumor tissues." (PMID 31752906, 2019). "We extracted proteins from the tumour tissues and evaluated the PCNA and Bax expression levels by western blotting." (PMID 30341797, 2019). "In view of these findings, PCNA has been proposed as an immune evasion mechanism, enhancing tumor cell survival by promoting a paradoxical NKp44-mediated inhibition of tumor cell killing by NK cells." (PMID 31024551, 2019). "Tumor tissues were homogenized, and proteins were isolated to detect the tumor proliferation marker PCNA by western blotting." (PMID 31637008, 2019). "In a subcutaneous xenograft mouse model, mice inoculated with oe-miR-5188-transfected HCC cells exhibited increased tumor burden and expression of Ki67 and PCNA compared with the control group." (PMID 31695788, 2019). "Compared with the levels in paired normal tissues, the levels of RAS were significantly increased together with those of proliferating cell nuclear antigen (PCNA) in the tumor tissues from patients with HCC." (PMID 30655611, 2019). "PCNA can be recruited to the plasma membrane of tumor cells, probably through the formation of a PCNA/HLA-I complex or shuttling via exosomes." (PMID 31024551, 2019). "PCNA (nuclear) staining was positive indicating the proliferative nature of the tumor with radiotracer uptake." (PMID 31703407, 2019). "We found that PCNA and Bcl-2 were increased in tumor cells co-cultured with activated 3T3, while the expression of Bax was decreased." (PMID 31167491, 2019). "The expression of proliferating protein PCNA was reduced in the tumor tissues of mice overexpressing RASSF1A gene." (PMID 31423110, 2019). "Tumor cell proliferation suppression was confirmed with PCNA immunohistochemical staining, showing that both Ame55 and cetuximab significantly decreased proliferating A431 tumor cell amount." (PMID 30733972, 2019). "To evaluate the proliferation modulating effects of recombinant IL-33 incubation and other administrated factors, we measured tumor growth, colony formation, cell viability, and the expression of Ki67 and proliferating cell nuclear antigen (PCNA)." (PMID 30119635, 2018). "Immunohistochemistry analysis demonstrated that the expression of Ki67 and PCNA was reduced after PF treatment, indicating that PF suppressed the proliferation of tumour cells." (PMID 29789528, 2018). "PCNA (a marker of tumor proliferation) expression was higher in nicotine-treated cells, indicating increased proliferation of hUC-MSCs by nicotine." (PMID 29416638, 2018). "Fewer tumor cells strongly positive for PCNA were observed at the TS-interface in the control group and hOCIF treatment did not significantly reduce the number of PCNA positive cells." (PMID 29547583, 2018). "The immunohistochemical results showed that both the staining intensity and the number of hyperproliferative Ki-67 and PCNA positive tumour cells were significantly increased after TFP treatment (P < 0.05)." (PMID 29348654, 2018).
tumor (continued). "IHC assay showed that PCNA was down‐regulated in the tumour tissues developed from Sox6 overexpressing PC cells, which was a marker for cell proliferation." (PMID 29369542, 2018). "And the results showed that the tumor treated with dioscin had a significant decrease in the expression of Bcl2, Ki67, and PCNA." (PMID 29497056, 2018). "Lastly, hematoxylin and eosin (H&E) stain and proliferating cell nuclear antigen (PCNA) expression were applied to HeLa tumor slices from different groups collected 24 h after one single injection and light irradiation." (PMID 29795534, 2018). "The immunohistochemistry of p-AKT, MMP9, and PCNA of the xenograft tumor were also consistent with the previous experiments." (PMID 29642505, 2018). "To summarize, our results show that NKp44-pep8 interact with PCNA in a specific manner and by targeting with intracellular PCNA, can lead to apoptosis of cancer cell lines in vitro and tumor growth arrest in vivo." (PMID 29875773, 2018). "Orally administered AA reduced the tumor volume and expression of proliferating cell nuclear antigen by promoting apoptosis in the mouse lung cancer xenograft model." (PMID 30233358, 2018). "The MC38 tumors grew more rapidly and the tumor Ki67 and PCNA were expressed at higher levels in IL-33 transgenic mice than in wild-type mice." (PMID 30119635, 2018). "The expression levels of both PCNA and Ki67 in the tumor specimens from the three treated groups were lower than those in the control group." (PMID 30326933, 2018). "Cell proliferation in the tumor region was evaluated based on the expression of proliferating cell nuclear antigen (PCNA) as a proliferation marker for immunohistochemical analysis." (PMID 29470420, 2018). "Since R11-NLS-pep8 showed the strongest reduction in PrestoBlue staining for both murine 4T1 and human A549 cell lines, we tested its binding affinity to PCNA and its functional efficacy on other murine and human tumor cell lines." (PMID 29875773, 2018). "To further confirm the tumour inhibition mechanism of PF, we examined the expression of Ki67, PCNA, β-catenin, Cyclin D1 and c-Myc in the tumour tissue." (PMID 29789528, 2018). "We therefore identified the NKp44 binding site to PCNA and further developed an NKp44-peptide-based agent that can inhibit tumor growth through interfering with the function of intracellular PCNA in the tumor cell." (PMID 29875773, 2018). "We found a very strong positive correlation between β-catenin and PCNA expression among all group of animals which suggest β-catenin plays important role in tumor promotion by stimulating tumor cell-proliferation." (PMID 30513115, 2018). "A reduction in tumour growth was accompanied by a decrease in proliferation (PCNA staining) and an increase in cell death (TUNEL staining)." (PMID 29567997, 2018). "In parallel with the decreased tumor growth, a lower expression level of proliferating cell nuclear antigen (PCNA) was observed in Sal-B treated and doxorubicin treated tumor xenografts than in untreated MDA-MB-231 tumor xenografts." (PMID 30555632, 2018). "To corroborate the effect of C19 on the proliferation of tumor cells in vivo, we did western blots to identify the expression of proliferating cell nuclear antigen (PCNA)." (PMID 30382908, 2018). "Both mouse and human tumor models were investigated since PCNA is a conserved protein with a high degree of homology across mammalian." (PMID 29875773, 2018). "To confirm the anti-angiogenic mechanism of rTSR1 in mouse tumor suppression, we performed double immunostainings of endomucin/PCNA and endomucin/cleaved caspase-3 to detect proliferating and apoptotic tumor endothelial cells, respectively." (PMID 29891754, 2018). "We observed decreased expression of proliferation marker PCNA and Ki67 at 24 h and 12 d pi; meanwhile, we also found radiation-induced DNA damage through cell cycle analyses of treated tumor." (PMID 30537980, 2018).